HSP90AA1 (heat shock protein 90 alpha family class A member 1)
Diseases named in the same sentence as HSP90AA1 in open-access papers (continued):
Sharing a sentence is not in itself a finding about the gene and the disease.
cancer (continued). "The results suggest that WWS exerts protective effects on gastric mucosa by modulating ferroptosis-related targets such as HSP90AA1 and MAPK, potentially through cancer-related signaling pathways." (PMID 41204487, 2025). "Conversely, HRP networks were characterized by the presence of Heat shock protein HSP90-alpha (HSP90AA1) and HSP90-beta (HSP90AB1), which are also important for cancer progression." (PMID 40136513, 2025). "Critical targets such as TNF, EGFR, ESR1, HIF1A, HSP90AA1, and SRC were involved in pathways including chemical carcinogenesis, PI3K‐Akt signaling, proteoglycans in cancer, receptor activation in chemical carcinogenesis, and immunomodulation." (PMID 40144560, 2025). "In this study, we developed a prediction model for the “inflammation-cancer transition” using six predictors: ARG2, HSP90AA1, EZH2, ICAM1, macrophage M1, and activated CD4 memory T cells." (PMID 40352921, 2025). "Particularly, the expression of INHBA, HSP90AA1 and EIF2AK2 in ESCC cancer tissues was significantly higher than that in normal tissues, while the level of LRRK2 and HSPB8 in ESCC tissues was remarkably lower as compared to the normal tissues." (PMID 39006030, 2024). "In cancers where HSPA4 expression significantly impacts prognosis, four genes—HSP90AA1, HSPA8, DNAJB1, and HSP90AB1—demonstrated a pronounced correlation." (PMID 38305786, 2024). "HSP90AA1 (Heat Shock Protein 90 Alpha Family Class A Member 1), as an important node in the PPI network, is a hot topic in the pathogenesis of malignant tumors." (PMID 37328788, 2023). "Screening 107 overall survival-related cancer genes and 402 interacting gene pairs, 6 genes: CRLF2, HSP90AA1, MAP2K1, PAFAH1B2, MYCL and SET genes, were identified and a transcriptional score was obtained." (PMID 37897503, 2023). "In contrast, the coefficients of SQSTM1, HSP90AA1, and STMN1 were positive, which was consistent with the reported function of promoting or suppressing cancer, indicating that DRGPI is a valuable prognostic biomarker for HCC patients." (PMID 35892599, 2022). "The expression levels of EGFR, HSP90AA1, and SRC at the transcriptional level of RC were significantly different between normal and cancer tissues (all p < 0.05)." (PMID 36569844, 2022). "The function of 6 NRGs in our signature, including FASLG, IPMK, FLT3, SLC39A7, HSP90AA1, and LEF1, are studied in various cancer types, including BC." (PMID 35864548, 2022). "In the top 20 upregulated DEGs of lymph node‐derived exhausted CD8+ T cells, CXCL13, CXCR4, CH25H, HSPD1, HSP90AA1, and ATF3 have been confirmed to promote lymph node metastasis in several cancer types." (PMID 35184420, 2022). "Numerous studies have demonstrated that HSP90AA1 and HSP90AB1 participate in tumorigenesis, and their overexpression promotes angiogenesis, metastasis, and differentiation of cancer cells." (PMID 36362498, 2022). "All the other regions were comprised of multiple genes, including a few known cancer genes according to COSMIC Cancer Gene Census v92: SLC34A2 on 4p15.2, RET on 10q11.21, HSP90AA1 on 14q32.31, and JAK3 on 19p13.11." (PMID 35922826, 2022). "At the transcriptional level of CC, EGFR, HSP90AA1, and SRC expression levels were significantly different between normal and cancer tissues (all p < 0.05)." (PMID 36569844, 2022). "Transcripts of the two most abundant HSP90 members, HSP90AA1 or HSP90AB1, are elevated in 17 out of 21 major human cancers." (PMID 35311075, 2022). "The results were further validated in the GTEX database; the correlation between HSP90AA1 and BRCA1 and CDK1 was only observed in cancer patients." (PMID 35095481, 2021).
cancer (continued). "To further explore the mechanism of HSP90AA1 regulation in cancer development, we tried to compare the differences between the HSP90AA1 correlated genes in normal (GTEX normal lung tissue) and cancer lung (TCGA LUAD) tissues." (PMID 35095481, 2021). "Furthermore, many experiments have shown that HSP90AA1 is able to promote cancer cell proliferation, metastasis, invasion, and epithelial-to-mesenchymal transition in several diseases, suggesting that HSP90AA1 could be a potential target for the treatment of cancers." (PMID 34109171, 2021). "Among the 24 potential genes, HSP90AA1, ANXA1, ARRDC4 and PSAT1 were involved with cancer progression." (PMID 34916487, 2021). "A statistically significant relationship was found between HSP90AA1 and HSPA4 overexpression and poor overall survival in cancer patients, as it is indicated by pooled hazard ratio (HR) values greater than 1 and p values less than 0.05." (PMID 31814876, 2019). "Among these 10 hubs are 5 – ACP1, HSP90AA1, LEF1, MLH1, and RBM5 - common to the major identified cancer-related pathways." (PMID 27809917, 2016). "Most of the genes, that are involved in many of the significantly enriched pathways, also play a role in pathways in cancer such as PTEN, JUN, AKT2, HSP90AA1, the latter of which was already described to influence radiosensitivity and chemosensitivity." (PMID 26328888, 2015). "Consistently, small molecular inhibitors of HSP90AA1 such as 17-AAG and SNX-2112 show promising results as cancer therapies." (PMID 25167922, 2014). "Our results demonstrated that 5 of the 6 up-regulated mRNAs in “HTLV-1 infection pathway” increased (ICAM1, WNT2B, MYC, HLA-F and TGF-β1) and 3 of the 5 down-regulated mRNAs in “Pathways in cancers” decreased (CDH1, PTENP1, HSP90AA1)." (PMID 24367666, 2013). "HSP90AA1 and HSP90AB1 facilitate oncogene addiction, critical for cancer progression." (PMID 39796173, 2025). "However, only AKT1, EGFR, BCL2, HSP90AA1, and PTGS2 exhibited strong binding affinities with pomegranate compounds, which are significantly declared in affected cells to enhance cancer progression." (PMID 40573291, 2025). "The results indicated markedly elevated levels of TXNDC9 and HSP90AA1 expression in the cancer tissues of CRC patients compared to their adjacent noncancerous tissues." (PMID 40184625, 2025). "Additionally, taking the biological function of HSP90AA1 as an entry point, the potential of PCC in cancer therapy was explored in this work." (PMID 39857345, 2024). "The majority of these genes were upregulated in Dual-R versus BTKi-R samples, including heat shock protein genes HSP90AB1 and HSP90AA1 (not shown), which are involved in protein folding and have been shown to promote cancer cell proliferation and migration." (PMID 38326887, 2024). "INHBA, HSP90AA1 and EIF2AK2 were overexpressed in cancer tissues and cells of ESCC." (PMID 39006030, 2024). "Through the PI3K-Akt, HIF-1, and ErbB signaling pathways, curcuma regulates key targets that are involved in angiogenesis, cancer cell proliferation, metastasis, invasion, and chemotherapy resistance, including AKT1, TNF, STAT3, EGFR and HSP90AA1, in the treatment of OS." (PMID 37311820, 2023). "This indicated that tissue type might not be an essential determinant contributing to ICD state of cancer patients; instead, a few high-expressed genes including CALR, HSP90AA1 and PDIA3 could regulate the process of ICD at a pan-cancer level." (PMID 36497433, 2022). "HSP90α protein is expressed at differing levels in a tissue‐specific manner and is specifically up‐regulated in several cancers, while the corresponding HSP90AA1 gene is not altered in the majority of tumors." (PMID 33331136, 2021).
cancer (continued). "The RNA expression levels of AHA1 and Hsp90aa1, but not Hsp90ab, were significantly higher in cancer tissues than in adjacent paired normal tissues (p = 0.032 and p = 0.0002, respectively)." (PMID 34620942, 2021). "In addition, the prognostic potential of HSP90AA1 and HSPA4 overexpression for cancer patients' overall survival was investigated." (PMID 31814876, 2019). "Also, we found that the expression levels of HSPA4 and HSP90AA1 and the detox enzyme gene CAT (catalase) are positively correlated in cancer." (PMID 31814876, 2019). "Moreover, the expression patterns of the thermogenes HSPA4 and HSP90AA1 and the oncogene PLK1 were found to be positively correlated in diverse types of cancers." (PMID 31814876, 2019). "Activating genes in this branch, first of all TERT, heat shock protein 90 (HSP90AA1, HSP90AB1), importin 7 (IPO7) and p23 (PTGES3) are overexpressed in cancer, while the heat shock protein 70 (HSPA1A) and CHIP ubiquitin ligase (STUB1), both acting as suppressors, are underexpressed." (PMID 31750255, 2019). "Furthermore, down-regulation of HSP90AA1 led to the degradation of its client proteins (PIM1 and AKT1), which are also cancer therapy targets." (PMID 25167922, 2014). "Quantitative comparisons revealed higher expression in malignant tumor cells, CD8+ T cells, and macrophages/monocytes, indicating a broad cellular expression pattern and suggesting that HSP90AA1 may contribute to UVM progression by modulating diverse cell populations within the TME." (PMID 41567202, 2025). "Pathways in cancer, central carbon metabolism in cancer, glycolysis/gluconeogenesis, and so on also suggested that isoscopoletin might affect the expression and activity of cancer-related proteins by binding to GPD2, GPI, Hsp90AA1 and PGK2." (PMID 39509399, 2024). "It included a number of genes with obvious cancer relevance including CD44, catenin b1 (CTNNB1), vimentin (VIM), cathepsins B and S (CTSB, CTSS), MMP9, XIAP, JunD, numerous proto-oncogenes (REL, YES, SET, FGR, CRK), and HSP90AA1 (which is a chaperone which stabilizes MIF as a client)." (PMID 28957348, 2017). "Consistently, silencing of HSP90AA1 in P3 cells but not in P0 cells and NANOG up-regulated human cancer cells markedly reduced the levels of them." (PMID 31992715, 2020).
tumor (170 papers, 2009 to 2026). "Emerging evidence suggests that HSP90AA1 plays important roles in multiple tumors, and it has been shown to interact with various tumor-associated proteins, regulating their biological activity and stability." (PMID 41507145, 2026). "Our results showed that HSP90AA1 expression was significantly downregulated in ccRCC, and its reduced expression was associated with tumor metastasis." (PMID 41507145, 2026). "Recent studies have shown that heat shock protein 90 alpha family class A member 1 (HSP90AA1) interacts with various tumor-associated proteins, regulates their biological activity and stability, and plays an important role in various tumors." (PMID 41507145, 2026). "Using the data from TCGA-KIRC for analysis, the results also revealed that HSP90AA1 expression was significantly reduced in ccRCC and that its low expression was associated with increased tumor stage and grade (T3/T4, G3/G4, and Stage III/IV)." (PMID 41507145, 2026). "High expression of HSP90AA1 was significantly associated with reduced disease-free survival, suggesting a link between its expression and aggressive tumor behavior." (PMID 41009692, 2025). "Only tumor subclones capable of upregulating HSP90AA1 can maintain proteostasis and survive this stress, rendering high HSP90AA1 expression a hallmark of the most aggressive and resilient tumor populations." (PMID 41567202, 2025). "HSP90AA1, for instance, encodes a heat shock protein, whose overexpression correlates with tumor progression and a poor prognosis in NSCLC, and has been shown to correlate with an exhausted phenotype of CD8 T cells in tumors." (PMID 39548591, 2024). "For instance, CRLF2 upregulation promotes tumor progression, while HSP90AA1 is linked to chemoresistance." (PMID 37897503, 2023). "Elevated expression of HSP90AA1 encoded protein is closely associated with the growth, proliferation, survival, and invasive capabilities of tumor cells." (PMID 37587188, 2023). "Collectively, these results suggest that miR-550a-3p directly targets HSP90AA1 and that the observed tumor-suppressive effects caused by miRNA ectopic expression are mediated, at least in part, by the interference with the HSP90 alpha-client protein axis." (PMID 35352023, 2022). "We next attempted to elucidate the underlying mechanism responsible for HSP90AA1 up-regulation in immune-edited tumor." (PMID 31992715, 2020). "In UVM, HSP90AA1 expression was tightly associated with the tumor immune microenvironment (TIME)." (PMID 41567202, 2025). "In addition, low expression of HSP90AA1 was associated with tumor metastasis." (PMID 41507145, 2026). "HSP90AA1, a molecular chaperone protein is significantly overexpressed in CC tissues compared to normal cervical tissues, especially in advanced CC, and is closely associated with the biological behaviors of tumor cells, including proliferation, metastasis, and drug resistance." (PMID 40352921, 2025). "As shown in circos diagram of MF, HSP90AA1 and CDH1 (E-Cadherin) were highly enriched in the cytoskeleton, suggesting that HSP90AA1 may profoundly change the characteristics of tumor cells through the cytoskeleton, thus causing the epithelial tumor cells may EMT." (PMID 37547757, 2023). "In this respect, diminishing HSP90AA1 expression in normal polyp-adjacent tissue along with increasing polyp potential for malignancy renders cellular proteins susceptible to stressors, which may translate into creating tumor-promoting environment." (PMID 34827586, 2021). "Interestingly, among these HSPs, overexpression of HSPA2 and DNAJC20 was associated with better prognosis (tumor suppressor-like activity), whereas high expression of other heat shock genes (HSP90AA1, CCT1, CCT2 and CCT6A) correlated with poor survival (oncogene-like activity)." (PMID 31101846, 2019). "Our results confirmed the downregulated expression of HSP90AA1 in ccRCC, and its reduced expression was closely related to distant tumor metastasis." (PMID 41507145, 2026).
tumor (continued). "HSP90AA1 (heat shock protein 90 alpha 1) regulates numerous oncogenic proteins involved in OS, and its overexpression enhances tumor cell survival and therapy resistance." (PMID 41158757, 2026). "After identifying the low expression characteristics of HSP90AA1 in ccRCC, it was essential to clarify the impact of increased HSP90AA1 expression on the tumor phenotype of ccRCC." (PMID 41507145, 2026). "The Human Protein Atlas (HPA) database was used to comprehensively characterize HSP90AA1 expression across normal and tumor tissues." (PMID 41567202, 2025). "Our findings further associate both metabolites with infections, neoplasms, and hyperphagia, showing strong binding affinities to STAT3, HSP90AA1, CASP3, CASP8, and SRC targets." (PMID 41295287, 2025). "Comparative analysis of TCGA and GTEx datasets revealed significantly decreased transcriptional levels of HSP90AA1 in UVM tumor tissues compared with normal ocular tissues (p = 1.5 × 10-12)." (PMID 41567202, 2025). "Second, while our in vivo xenograft model confirmed the role of HSP90AA1 in promoting intrinsic tumor growth, nude mice lack functional T cells." (PMID 41567202, 2025). "Typically, the high HSP90AA1 expression levels have been detected in numerous malignant growth and invasive tumor samples." (PMID 40230723, 2025). "We observed lower transcriptional levels of HSP90AA1 in tumor tissues compared to normal eye tissues." (PMID 41567202, 2025). "Single-cell analysis revealed that HSP90AA1 is widely expressed across multiple cell types within the UVM tumor microenvironment, particularly in malignant cells, CD8+ T cells, and macrophages." (PMID 41567202, 2025). "HSP90AA1 is a molecular chaperone protein that promotes tumor cell survival by stabilizing a variety of oncogenic proteins, such as kinases, transcription factors, and hormone receptors." (PMID 40740310, 2025). "Using systems pharmacology, we identified 50 anti‐HCC core targets, including EGFR, c‐Myc, ERBB2, ESR1, CCND1, and HSP90AA1, all of which play critical roles in tumor initiation, proliferation, angiogenesis, and resistance mechanisms." (PMID 40727254, 2025). "As a member of the Heat Shock Protein 90 (HSP90) family, HSP90AA1 plays a significant role in cellular processes relevant to tumor progression." (PMID 40141751, 2025). "Studies have also suggested that the HSP90AA1 protein product HSP90α plays a key role in regulating tumor invasion and migration." (PMID 39113883, 2024). "Collectively, these results suggested that HSP90AA1 can act as a tumor promoting factor via promoting the invasion, migration and inhibiting apoptosis of HNSCC cells." (PMID 38713284, 2024). "The mRNA expression of RXRα, AKT1, ESR1, MAPK1, and HSP90AA1 in tumor and normal tissues was analyzed using the GEPIA database." (PMID 38835342, 2024). "Our approach provided a significant number of genes related to T cell function in the tumor microenvironment, including HSP90AA1, ETS1, CXCR4, RGS1, and FYN, all detected at the gene level." (PMID 39548591, 2024). "Among the four ICDGs, HSP90AA1 was highly expressed in tumor tissues and served as a significant survival indicator in multiple cohorts." (PMID 38713284, 2024). "In comparison with normal tissues, HNSCC tumor tissues showed significant overexpression of HSP90AA1." (PMID 38713284, 2024). "Recent studies have indicated that activation of HSP90AA1 promotes tumor progression, invasion, and chemotherapy resistance." (PMID 38166541, 2024). "Current research on HSP90AA1 focuses on its role as a drug target due to its interaction with a variety of tumor-promoting proteins and its role in cellular stress adaptation, including AKT1." (PMID 38927034, 2024). "HSP90AA1 acts as an extracellular secretory factor involved in inflammation, facilitating the malignant phenotype formation in tumor cells." (PMID 38166541, 2024). "The mRNA expression of RXRα, AKT1, ESR1, MAPK1, and HSP90AA1 was analyzed in different tumor tissues." (PMID 38835342, 2024).